ZFAS1 (ZNFX1 antisense RNA 1)
Diseases named in the same sentence as ZFAS1 in open-access papers (continued):
Sharing a sentence is not in itself a finding about the gene and the disease.
Hyperammonemia (1 paper, 2022). An increased concentration of ammonia in the blood. "Taken together, our results suggest that both ZFAS1 and GAS5 exert proapoptotic effects during NH4Cl-induced hyperammonemia." (PMID 35464767, 2022). "Our data revealed the roles of lncRNAs, ZFAS1, and GAS5, on neuronal cell death and neural structure in hyperammonemia in in vivo and in vitro conditions." (PMID 35464767, 2022). "Thus, ZFAS1 and GAS5 lncRNAs may contribute to hyperammonemia-induced neuronal injury and cell death." (PMID 35464767, 2022).
intervertebral disc degeneration (1 paper, 2022). "We investigated the function of lncRNA zinc finger antisense 1 (ZFAS1) in intervertebral disc degeneration (IDD) progression in vitro and in vivo." (PMID 36561842, 2022).
invasive ductal breast carcinoma (1 paper, 2016). The most common type of invasive breast carcinoma, accounting for approximately 70% of breast carcinomas. "ZFAS1 is expressed in mouse mammary gland tissues, and was previously found to be downregulated in human invasive ductal breast carcinoma, as compared to normal breast tissue." (PMID 27871336, 2016). "Given its role in mammary epithelial proliferation and differentiation, ZFAS1 expression was compared in human invasive ductal carcinoma and in normal breast tissue, and was found to be decreased in abundance in the former." (PMID 27871336, 2016).
laryngeal carcinoma (1 paper, 2024). Carcinoma that arises from the laryngeal epithelium. "In laryngeal cancer, several lncRNAs, such as ZFAS1, AFAP1-AS1, and NEAT1, have been shown to be key players in malignant progression." (PMID 38967843, 2024). "For example, DLX6-AS1, NEAT1, ZFAS1 and NKILA regulate the progression of laryngeal cancer through different regulatory mechanisms." (PMID 38967843, 2024).
multiple sclerosis (1 paper, 2025). A progressive autoimmune disorder affecting the central nervous system resulting in demyelination. "Considering that herpesviruses have been linked to neurological disorders including mesial temporal lobe epilepsy and multiple sclerosis, ZFAS1 may represent a potential therapeutic target for modulating neuroinflammation in virus-associated neurological diseases." (PMID 41214723, 2025).
Myocardial fibrosis (1 paper, 2021). "Specifically, inhibition of ZFAS1 could potentially alleviate myocardial fibrosis in DbCM by inhibiting cardiomyocyte ferroptosis by sponging miR‐150‐5p to activate CCND2." (PMID 34609043, 2021).
nervous system cancer (1 paper, 2017). A primary or metastatic malignant neoplasm involving the nervous system. "Further subgroup meta-analysis demonstrated that ZFAS1 could be a reliable prognostic biomarker for digestive system cancers, nervous system cancers and respiratory system cancers." (PMID 29245995, 2017).
oligoastrocytoma (1 paper, 2017). A WHO grade II tumor composed of a conspicuous mixture of two distinct neoplastic cell types morphologically resembling the tumor cells in oligodendroglioma and diffuse astrocytoma. "ZFAS1 was overexpressed in oligodendroglioma and oligoastrocytoma when cross tested with primary GBMs, which showed near normal expression levels." (PMID 29138748, 2017).
Papillary Thyroid Carcinoma (1 paper, 2021). "This study aimed to investigate the role of long noncoding RNA (lncRNA) ZFAS1 in the metastasis of papillary thyroid carcinoma (PTC) and the potential molecular mechanisms." (PMID 34249125, 2021).
rectal tumor (1 paper, 2020). "For example, rectal tumor organoids showed a diminished expression of the colorectal tumorigenesis suppressor ERBIN7 and increased expression of the mTORC1 activator LAMTOR4 and the protumorigenic gene ZFAS1." (PMID 32824266, 2020).
temporal lobe epilepsy (1 paper, 2025). A localization-related (focal) form of epilepsy characterized by recurrent seizures that arise from foci within the temporal lobe, most commonly from its mesial aspect. "Furthermore, ZFAS1 has been previously associated with neuroinflammatory conditions such as temporal lobe epilepsy and neuropathic pain, suggesting that its regulatory functions may extend to broader CNS pathologies." (PMID 41214723, 2025).
xeroderma pigmentosum (1 paper, 2025). Xeroderma pigmentosum (XP) is a rare genodermatosis characterized by extreme sensitivity to ultraviolet (UV)-induced changes in the skin and eyes, and multiple skin cancers. "However, ZFAS1‐depleted cells showed moderate UDS reduction compared to severely impaired xeroderma pigmentosum C (XP‐C, GG‐NER‐deficient) cells, indicating dual NER pathway impairment." (PMID 40411394, 2025).
tumor (110 papers, 2016 to 2026). "Our multi-omics investigation further established ZFAS1 overexpression patterns specifically associated with tumor progression markers including TNM staging and patient age (all P < 0.05)." (PMID 41450817, 2026). "Initially, ZFAS1, a novel tumor-associated lncRNA, was found to enhance epithelial-mesenchymal transition, migration, and cell proliferation." (PMID 39001904, 2024). "Overexpressed levels of ZFAS1 are associated with decreased tumor cell proliferation leading to apoptosis of BC cells." (PMID 37737288, 2023). "The results indicated that ZFAS1 overexpression significantly reversed the inhibition of tumor growth caused by IMP2 silencing in the xenograft mouse model." (PMID 34743750, 2021). "Only ZFAS1 was significantly associated with tumor progression, and its high expression predicted poorer overall (p = 0.01) and disease-free (p = 0.042) survival in HCC patients." (PMID 34072570, 2021). "High ZFAS1 expression was significantly associated with aggressive tumor phenotypes and poorer overall survival in HB." (PMID 31781561, 2019). "Notably, ZFAS1 has been implicated in enhancing glycolysis and tumor proliferation via its interaction with key metabolic regulators." (PMID 40697388, 2025). "ZFAS1 knockdown was also associated with decreased tumor growth in an in vivo mouse model." (PMID 33771981, 2021). "Primary progression at first tumor assessment, performed after two months of vemurafenib therapy, was linked with pretreatment plasma upregulation of 7SL and Zeb2NAT and downregulation of Zfas1 and AIR." (PMID 31231466, 2019). "This meta-analysis revealed that the expression of ZFAS1 was associated with tumor prognosis." (PMID 30544408, 2018). "Mechanistically, ZFAS1 functions as a competitive endogenous RNA (ceRNA) that sequesters tumor-suppressive miRNAs including miR-150 and miR-193a-3p, thereby de-repressing downstream oncogenic targets such as ZEB1/MMP14 and RALY/HGF/c-Met." (PMID 41450817, 2026). "Future research must employ single-cell dual-omics (simultaneously measuring lncRNA and miRNA expression) and spatial transcriptomics to determine the co-localization and cell-type specificity of these ZFAS1-miRNA axes within the tumor microenvironment." (PMID 41450817, 2026). "For instance, ZFAS1 exhibits high expression in GC tumor tissues, promoting the migration and invasion of GC cells by regulating epithelial‐mesenchymal transition." (PMID 39668941, 2025). "Six genes—ARHGEF19, CORO1A, ACOT7, ZC3H18, SLC5A5, and ZFAS1—showed statistically significant differential expression between tumor and normal tissues (P < 0.05)." (PMID 40070828, 2025). "Genes with a hazard ratio <1, such as OR2A1-AS1 and UGDH-AS1, were considered tumor suppressors, while ZFAS1, which has a hazard ratio >1, was considered an oncogene." (PMID 38707466, 2024). "The expression levels of ZFAS1 were evaluated in 23 primary tumor types using The Cancer Genome Atlas (TCGA) dataset." (PMID 39296014, 2024). "In particular, ZFAS1 expression was markedly elevated in HCC tumor tissues compared to normal tissues." (PMID 39296014, 2024). "Loss-of-function assays showed that knockdown of ZFAS1-inhibited NSCLC cell proliferation and invasive potentials increased the rate of apoptosis of NSCLC cells in vitro and attenuated tumour growth of NSCLC cells in nude mice." (PMID 38166659, 2024). "RT–qPCR results showed that LINC00924, LINC00944, and LINC00865 were highly expressed in tumour tissues, while LINC00702 and ZFAS1 were expressed at low levels in tumour tissues." (PMID 36936957, 2023). "ESCC cells exosomes transferred oncogene lncRNA ZFAS1 to the surrounding cells to facilitate tumor growth." (PMID 36854894, 2023). "Then, we examined the levels of these sMRLNRs which were used to establish the MRRS in various LUAD tissues and cell lines, and found that ZFAS1 expressed highly in tumor tissues and showed the inverse results compared to SH3BP5-AS1 and AL359220.1." (PMID 37566767, 2023).
tumor (continued). "ZFAS1 expressed highly in tumor tissues and showed the inverse results compared to SH3BP5-AS1 and AL359220.1." (PMID 37566767, 2023). "It appeared that ZFAS1 was consistently expressed at higher levels in ccRCC tumor cell lines than in the normal renal tubular epithelial cell line." (PMID 36902032, 2023). "Patients with high ZFAS1 expression are more likely to show more advanced grading, staging and tumor status than patients with low ZFAS1 expression." (PMID 36855431, 2023). "Compared to nearby non-tumor tissues, it was discovered that the expression of lncRNA ZFAS1 in ccRCC was considerably elevated." (PMID 36902032, 2023). "Initially, ZFAS1 was identified as a new tumor-related lncRNA by upregulating cell proliferation, migration and EMT." (PMID 36855431, 2023). "Meanwhile, the results of immunohistochemistry staining in tumor tissues collected from the mice showed that downregulation of ZFAS1 led to decreased protein levels of SREBP1 and SCD1, which is consistent with the in vitro findings." (PMID 35036050, 2022). "Accumulating evidence indicates that long non-coding RNA zinc finger antisense 1 (ZFAS1) is a novel lncRNA with potential functions in human cancer pathology and physiology, which is involved in tumorigenesis and tumor progression." (PMID 36211292, 2022). "Using qPCR, we analysed the expression of DCN, miR-200c and five lncRNAs (LUCAT1, MALAT1, lncTCF7, XIST, and ZFAS1) in lymph node and liver metastases in comparison to the invasive front and central part of a primary tumour." (PMID 35052821, 2022). "First, we detected the expression of ZFAS1 in tumor tissues and adjacent tissues of 53 NPC patients and found that it was highly expressed in tumor tissues (p < 0.05)." (PMID 34980191, 2022). "ZFAS1 was initially reduced in breast cancer tissue, suggesting that this transcript has tumor-suppressive effects." (PMID 35846429, 2022). "In our in vivo experiment, knockdown of ZFAS1 significantly decreased CC tumor volume generated by SiHa cell or CaSki cells (p < 0.01)." (PMID 35112985, 2022). "The Chi square test revealed that ZFAS1 expression was tightly associated with tumor FIGO stage and tumor diameter (p < 0.01)." (PMID 35112985, 2022). "Based on the relative ZFAS1 expression in tumor tissues, the 30 CRC patients were classified into two groups: the high-ZFAS1 group (n = 20, fold change ≥2) and the low-ZFAS1 group (n = 10, fold change < 2)." (PMID 35036050, 2022). "In this study, we found that the expression of ZFAS1 was higher in both CRC tissues and cell lines, and ZFAS1 overexpression was positively correlated with advanced pathological stages and larger tumor sizes." (PMID 35036050, 2022). "Our results showed insignificant upregulation of DCN and significant upregulation for miR-200c, MALAT1, lncTCF7 and ZFAS1 in metastases compared to the primary tumour." (PMID 35052821, 2022). "Our results show that the up-regulation of ZFAS1 can regulate the autophagy level of tumor cells, and this regulation makes tumor cells have stronger cell viability and migration ability." (PMID 34980191, 2022). "With the development of further research, many studies reported that ZFAS1 is overexpressed in and promotes the malignant progression of many types of human tumours." (PMID 34552050, 2021). "Nevertheless, T. Wang reports that ZFAS1 regulates methylation of miR-9 and is a potential tumor suppressor in HCC." (PMID 35198599, 2021). "Compared with the control group, tumour growth was inhibited in the ZFAS1 knockdown group from 25 to 35 days, and this inhibitory effect was reversed by HMGA2 plasmid." (PMID 34552050, 2021). "ZNFX1 antisense RNA1 (ZFAS1), located on chromosome 20q13, is a newly identified tumour-related lncRNA." (PMID 34552050, 2021). "We validated the expression of ZFAS1, identifying it as a major regulator of tumor progression in CRC, through the critical miR-200/ZEB1/E-cadherin, vimentin signaling cascade." (PMID 33771981, 2021).
tumor (continued). "T. Li’s research suggests that ZFAS1 bonds miR-150 and abrogates its tumor-suppressive function to be an oncogene in HCC development." (PMID 35198599, 2021). "Evidences have shown that ZFAS1 (ZNFX1 antisense RNA 1) can function either as a tumor suppressor or as a tumor promoter, depending on the type of cancer cell." (PMID 32760219, 2020). "Both lncRNAs have been assigned tumor suppressive functions in human breast cancer, whereas ZFAS1 seems to be a potent oncogenic lncRNA in other tumor types." (PMID 33076269, 2020). "The authors report that the tumor suppressor miRNA, miR-193a-3p, was elevated in ZFAS1 knockdowns which, confirmed by luciferase reporter assay and correlation analysis, suggested that the prooncogenic role of ZFAS1 relied on the suppression of miR-193a-3p." (PMID 33299889, 2020). "In platelets and plasma of NSCLC patients, MAGI2-AS3 and ZFAS1 were downregulated and their expression significantly correlated with tumor stage." (PMID 33076269, 2020). "UALCAN and GEPIA, which are both online tools based on The Cancer Genome Atlas (TCGA), showed correlations between the ZFAS1 expression level and patient sex, tumour grade and drinking habits." (PMID 32550827, 2020). "Specifically, ZFAS1 depletion results in a dramatically suppression in tumor weight at the days of 30 compared with the NC group." (PMID 33202381, 2020). "From these results, the authors concluded that ZFAS1 was acting in an oncogenic role by binding miR‐150 and abrogating its tumour‐suppressive function in HCC progression." (PMID 30288832, 2019). "Among them, ZFAS1 is dysregulated and acts as either an oncogene or a tumor suppressor in various human malignancies." (PMID 31186036, 2019). "Knockdown of ZFAS1 significantly inhibited tumor growth as shown by luciferase photon flux and tumor volume at different time points after implantation." (PMID 31781561, 2019). "LncRNA ZFAS1 expression was relatively up‐regulated in tumour tissues and cells while miR‐296‐5p was significantly down‐regulated." (PMID 31565837, 2019). "Silencing of ZFAS1 contributed to suppressed proliferation, migration, invasion and tumor growth in vitro and induced apoptosis of ESCC cells." (PMID 31775815, 2019). "Here, we found that one validated coding smORF derived from ZFAS1 was upregulated in HCC tumor tissue and nearly unexpressed in normal liver tissue." (PMID 31781169, 2019). "After validating the role of ZFAS1 as an oncogene in CCA, the underlying mechanisms of tumour malignant behaviours aroused our interest." (PMID 31565837, 2019). "As our lab focused on HCC pathological investigation and previous studies have shown ZFAS1 can exert their functions by lncRNAs in HCC, the expression level of ZFAS1 was further validated in 32 pairs of HCC/non-tumor tissue specimens using RT-qPCR." (PMID 31781169, 2019). "In the present study, ZFAS1 was firstly found to have a similar expression trend as in other tumours that ZFAS1 was up‐regulated in CCA human tissues compared to the adjacent normal tissues." (PMID 31565837, 2019). "Knockdown of ZFAS1 significantly suppressed tumour proliferation, migration, invasion and USF1 expression." (PMID 31565837, 2019). "We also observed that ZFAS1, acting as a miR-150-5p sponge, promoted tumor growth, metastasis, and angiogenesis in CRC." (PMID 30250022, 2018). "Several exosomal lncRNAs, such as MALAT-1, linc-POU3F3, ZFAS1, promote tumor growth and migration, prevent tumor cell apoptosis, or induce angiogenesis." (PMID 29456536, 2018). "ZNFX1 antisense RNA1 (ZFAS1) has been reported to be aberrant expression and suggested as a tumor suppressor or oncogene in many cancers." (PMID 30250022, 2018). "ZNFX1 antisense RNA1 (ZFAS1), located on chromosome 20q13, has been firstly reported to be dysregulated and suggested as a tumor suppressor gene in breast cancer." (PMID 30250022, 2018).